STK32A (serine/threonine kinase 32A)
Description:
Probable serine/threonine kinase with currently unidentified substrates. In the inner ear, functions as a planar cell polarity (PCP) factor acting antagonistically to EMX2. It regulates the orientation of stereociliary bundles in hair cells by interacting with the PCP signaling pathway in opposition to EMX2. Additionally, it may play a role in controlling the apical localization of the GPR156 receptor in inner ear hair cells.
Synonyms: YANK1; MGC22688
Tractability: Small molecule: a structure with a bound ligand is known; a high-quality ligand is known; it belongs to a druggable protein family. Antibody: UniProt places it where antibodies can reach, with medium confidence; its Gene Ontology location is reachable by antibodies, with medium confidence. PROTAC: a small molecule that binds it is known.
Target class: Kinase; AGC protein kinase YANK family; Enzyme; Protein Kinase; AGC protein kinase group
Gene: Protein-coding gene on chromosome 5 (147,234,963 to 147,387,855, forward strand). Ensembl gene ENSG00000169302.
Subcellular location: Cell membrane
Subcellular location (Human Protein Atlas): Centrosome
Gene Ontology:
Molecular function: protein serine kinase activity; protein serine/threonine kinase activity; ATP binding; protein kinase activity
Biological process: intracellular signal transduction
Cellular component: plasma membrane
Genetic constraint (gnomAD): Loss-of-function variants: 37 observed, 42.05 expected, observed/expected ratio (o/e) 0.88, 90% interval 0.68 to 1.16. The upper end of that interval is the gene's LOEUF score, 1.16, which puts it in group 5 of 6, group 1 being the genes least tolerant of losing a copy. Missense variants: 400 observed, 432.14 expected, observed/expected ratio (o/e) 0.93, 90% interval 0.85 to 1. Synonymous variants: 153 observed, 146.64 expected, observed/expected ratio (o/e) 1.04, 90% interval 0.91 to 1.19.
Homologues: Orthologues: chimpanzee STK32A (96% identical), macaque STK32A (96% identical), rabbit STK32A (93% identical), pig STK32A (91% identical), guinea pig STK32A (91% identical), mouse Stk32a (91% identical), dog STK32A (90% identical), rat Stk32a (90% identical), tropical clawed frog stk32a (75% identical), Drosophila melanogaster CG32944 (51% identical), Caenorhabditis elegans M03C11.1 (41% identical), Drosophila melanogaster dop (29% identical), and 3 more. Paralogues in human: STK32B (69% identical), STK32C (64% identical), MAST1 (32% identical), MAST2 (32% identical), MAST3 (32% identical), MAST4 (31% identical), SGK2 (27% identical), SGK3 (26% identical), LATS2 (26% identical), LATS1 (24% identical), SGK1 (24% identical), MASTL (23% identical), and 1 more.
Diseases named in the same sentence as STK32A in open-access papers:
STK32A is named in the same sentence as 14 diseases in open-access papers, as found by Europe PMC text mining. Sharing a sentence is not in itself a finding about the gene and the disease. The quoted sentences say what the papers report.
lung carcinoma (4 papers, 2013 to 2025). "Serine/threonine kinase 32A (STK32A) has been confirmed by epidemiological investigations as a susceptibility gene for lung cancer." (PMID 38111060, 2023). "Overexpression of STK32A enhances migration and proliferation of lung cancer cells while inhibiting apoptosis, which is essential for lung cancer progression." (PMID 38111060, 2023). "We identified methylation changes in three genes, VTI1A, STK32A and GATA3 that were rarely reported in relation to lung cancer among Caucasians previously." (PMID 27323854, 2016).
non-small cell lung carcinoma (3 papers, 2021 to 2025). A group of at least three distinct histological types of lung cancer, including non-small cell squamous cell carcinoma, adenocarcinoma, and large cell carcinoma. "A pro-EMT role for the RUNX2/STK32A/NF-κB p65 axis was uncovered in non-small-cell lung cancer (NSCLC)." (PMID 37108164, 2023). "STK32A participates in cellular homeostasis, cell-cycle modulation, and phosphorylation of transcription factors, and can modulate the invasion and metastasis of non-small cell lung cancer." (PMID 34308747, 2021).
asthma (1 paper, 2015). "Others have been associated with diabetes (ZBED3), asthma (EMID2), and cancer (FBXO3, HOOK2, MT2A, EIF3E, RPH3AL, PTRF, MT1M, STK32A)." (PMID 25748564, 2015).
metastatic melanoma (1 paper, 2023). A melanoma that has spread from its primary site to another anatomic site. "Although prior knowledge of STK32A is limited, it has been linked to stomach adenocarcinoma (STAD) where its overexpression is associated with lower overall survival, and somatic mutations in Stk32a have also been identified in neuroendocrine carcinoma of the lung and metastatic melanoma." (PMID 37144879, 2023).
squamous cell carcinoma (1 paper, 2023). A carcinoma arising from squamous epithelial cells. "This comparison showed an overlap of five genes (ETV4 (tumor non-malignant signature), STK32A, SPINK1, GOLT1A, KRT6A (adenocarcinomas—squamous cell carcinomas signature)) in the first case, and an overlap in one (KRT15) of the three most prominent genes in the second case." (PMID 36832225, 2023).
cancer (3 papers, 2015 to 2026). A tumor composed of atypical neoplastic, often pleomorphic cells that invade other tissues. "Similarly, Mitogen-Activated Protein Kinase 4 (MAPK4) in 12 cancers, Serine/Threonine Kinase 32A (STK32A) and P21 (RAC1) Activated Kinase 3 (PAK3) in 10 cancers were found to be commonly downregulated." (PMID 33801837, 2021). "One of them included the STK32A gene which was found to be downregulated in 10 cancers." (PMID 33801837, 2021). "In complete responders, skin lesion RNA sequencing after treatment, compared with baseline, identified increased inflammation (CXCL5, CXCL8, IL1A, COL1A1) and downregulated cancer markers (PRAME, S100B, MLANA, STK32A)." (PMID 42316430, 2026).
tumor (3 papers, 2022 to 2025). "In NSCLC, the microRNA-130a-5p/RUNX2/STK32A network modulates tumor proliferation, metastasis, and invasion." (PMID 36551878, 2022).
STK32A also shares sentences with these, for which no sentence is quoted: papillary thyroid carcinoma (2 papers); adenocarcinoma (1); diabetes (1); Huntington disease (1); lung adenocarcinoma (1); thyroid cancer (1); thyroid tumor (1).